ZAP70 (zeta chain of T cell receptor associated protein kinase 70)
Diseases named in the same sentence as ZAP70 in open-access papers (continued):
Sharing a sentence is not in itself a finding about the gene and the disease.
renal cell carcinoma (2 papers, 2021 to 2025). "Among these, EGFR and CD4 exhibited a protective role in renal cell carcinoma, whereas TRIB3 and ZAP70 were identified as risk factors (P - value <0.05)." (PMID 40104395, 2025). "This HTDS assay revealed that Staurosporine, AZD7762, and Sunitinib [an FDA approved drug for renal cell carcinoma (RCC) and imatinib-resistant gastrointestinal stromal tumor (GIST)] from the compound library can effectively inhibit the ZAP70 activity." (PMID 34413312, 2021).
respiratory infections (2 papers, 2020 to 2026). "ZAP-70 deficiency manifests clinically in a variety of ways, including recurring respiratory infections and cutaneous manifestations." (PMID 41790376, 2026). "Patients with ZAP-70 deficiency present with a variety of clinical manifestations, particularly recurrent respiratory infections and cutaneous involvements." (PMID 32431715, 2020).
sarcoma (2 papers, 2019). A usually aggressive malignant neoplasm of the soft tissue or bone. "Records in the latest version of CTD, a publicly available database curated information about environmental factors affecting human health, indicated that ZAP70 was one of disease genes for sarcoma." (PMID 31345171, 2019).
actinopathy- (1 paper, 2024). "This contrasts with the deficiency of other actinopathy-associated proteins such as WASP, CARMIL2 for which normal ZAP70 activation was reported, however TCR signaling beyond ZAP70 has been shown to be impaired in those deficiencies." (PMID 39120629, 2024).
atopic dermatitis (1 paper, 2021). "We present a 6-year-old male patient with markedly elevated IgE and severe atopic dermatitis presenting with staphylococcal bacteremia found to have a heterozygous variant in FLG (p.S3247X) and multiple variants of unknown significance in BCL11B, ZAP70, LYST, and PTPRC." (PMID 34603803, 2021).
autoimmune thyroid disease (1 paper, 2024). Inflammatory disease of the thyroid gland due to autoimmune responses leading to lymphocytic infiltration of the gland. "The ZAP70 T155M variant associated with autoimmune thyroid disease appears to act through a similar mechanism of impaired TCR signaling resulting in loss of tolerance." (PMID 39041034, 2024).
Burkitt lymphoma (1 paper, 2020). A rare form of malignant mature B-cell non-Hodgkin lymphoma. "Interestingly, despite the dispensable nature of its kinase activity, ectopic expression of ZAP-70 in the Burkitt lymphoma line BJAB enhanced the phosphorylation and activation of BCR-related signaling cascades under conditions of IgM activation." (PMID 33194762, 2020).
CNS leukemia (1 paper, 2020). "Targets of these microRNAs included proteins associated to CNS leukemia, e.g., Zeta Chain of T Cell Receptor Associated Protein Kinase 70 (ZAP70) and C-X-C modif chemokine ligand 12 (CXCL12)." (PMID 32752027, 2020).
deficiencies (1 paper, 2017). "Based on the developed protocol, it would be interesting to validate further this protocol to cover a broad range of T cell deficiencies, including mutations in the genes encoding ZAP70, CD3Z and CD45, in order to address different blocks in T cell development." (PMID 28963568, 2017).
DNA repair disorder (1 paper, 2017). "If it has a role in B cell survival, particularly after a critical insult, such as ionizing radiation-induced DNA damage, loss of ZAP70 function could result in augmented radiation sensitivity, as assessed by the clinical in vitro DNA repair disorder assay." (PMID 28603521, 2017).
experimental autoimmune encephalomyelitis (1 paper, 2025). An autoimmune demyelinating disease of the central nervous system that is produced experimentally in animals by the injection of homogenized brain or spinal cord in Freund's adjuvant. "In this study, we aimed to determine whether P. gingivalis promotes peripheral Th1 cell differentiation via the ZAP70/NF-κB signaling pathway, thereby exacerbating experimental autoimmune encephalomyelitis(EAE), a model of multiple sclerosis." (PMID 40170858, 2025).
Failure to thrive (1 paper, 2025). Failure to thrive (FTT) refers to a child whose physical growth is substantially below the norm. "Infants with ZAP70 deficiency typically present with recurrent infections, such as severe respiratory tract infections and oral candidiasis, along with failure to thrive." (PMID 40901120, 2025).
fibrosis (1 paper, 2022). the formation of excess fibrous connective tissue in an organ or tissue in a reparative or reactive process. "Among these genes, the expression of inflammation-associated FCER1G, OSM, VEGFA, and ZAP70 was lower in high-grade fibrosis than in low-grade fibrosis, whereas CHIT1 expression, which is associated with fibrogenic activity of macrophages, was higher in high-grade fibrosis." (PMID 35052861, 2022).
follicular lymphoma (1 paper, 2019). Follicular lymphoma is a form of non-Hodgkin lymphoma characterized by a proliferation of B cells whose nodular structure of follicular architecture is preserved. "Taken together, we show here that rituximab exerts beneficial effects especially in the subgroup of follicular lymphoma patients with low intrafollicular CD3, CD5, ZAP70 and CD8, and high CD56 and CD68 expression." (PMID 31273513, 2019). "We show here that rituximab exerts beneficial effects, especially in the subgroup of follicular lymphoma patients with low intrafollicular CD3, CD5, CD8, and ZAP70 and high CD56 and CD68 expression." (PMID 31273513, 2019).
HIV-1 infection (1 paper, 2016). The type species of lentivirus and the etiologic agent of acquired immunodeficiency syndrome (AIDS). "Our results showed that pH1N1 infection increased more Zap-70 and PKCɵ expression on plasma membranes relative to HIV-1 infection alone." (PMID 26848681, 2016).
hypothyroidism (1 paper, 2025). Abnormally low levels of thyroid hormone. "We observed converging evidence linking both common and rare PAVs in TYK2 and ZAP70 with reduced risk of hypothyroidism." (PMID 41238958, 2025).
infantile-onset multisystem autoimmune disease type 2 (1 paper, 2025). "Other pathogenic ZAP70 variants have been linked to autosomal recessive conditions, such as infantile-onset multisystem autoimmune disease type 2 and immunodeficiency type 48." (PMID 40901120, 2025).
Mycobacterium infection (1 paper, 2021). Infections with bacteria of the genus Mycobacterium. "The role of the remaining 7 genes (CD2, CD6, CD247, ZAP70, CD3D, SH2D1A, and CD3E) in T-cell signaling and modulation of host immune responses in mycobacterium infections is also supported." (PMID 35198572, 2021).
neuroblastoma (1 paper, 2019). Neuroblastoma (NB) is the most common solid, extracranial childhood tumor. "We screened the neuroblastoma cell lines used in this study for ZAP-70 presence and found it expressed at protein level only in SK-N-DZ cells." (PMID 30744170, 2019).
pancreatic cancer (1 paper, 2022). "Several proteins with known roles in tumorigenesis such as FN1, TSPO, CD3E, and ZAP70 were present in the modules, which may be explored further as novel drug targets in pancreatic cancer." (PMID 36923555, 2022).
periodontitis (1 paper, 2025). An acute or chronic inflammatory process that affects the tissues that surround and support the teeth. "This indicates that P. gingivalis LPS plays a crucial role in promoting Th1 cell differentiation by activating the ZAP-70/NF-κB signaling pathway, promoting MS associated with periodontitis." (PMID 40170858, 2025). "Future studies must explore the ZAP70/NF-κB signaling pathway and molecular mechanisms by which periodontitis exacerbates EAE in vivo." (PMID 40170858, 2025). "Through activation of the ZAP70/NF-κB signaling pathway by P. gingivalis LPS, periodontitis promoted the differentiation of peripheral blood Th1 cells, increased the permeability of the BBB, and enhanced inflammatory infiltration and demyelination of the CNS, intensifying the severity of EAE." (PMID 40170858, 2025).
pneumocystis pneumonia (1 paper, 2023). "Genetic characterization of an infant who presented with pneumocystis pneumonia, mycobacterial infection, and an absence of CD8 T cells revealed a novel homozygous mutation in the C-terminal SH2 domain (SH2-C) of the ZAP70 gene (c.C343T, p.R170C)." (PMID 37313400, 2023).
primary ciliary dyskinesia (1 paper, 2025). A rare, genetically heterogeneous, primarily respiratory disorder characterized by chronic upper and lower respiratory tract disease. "The patient was found to carry a homozygous ZAP70 splice-site variant (c.402 + 2 T>C), which was previously reported in a patient with primary ciliary dyskinesia." (PMID 40901120, 2025).
protein deficiency (1 paper, 2016).
pulmonary fibrosis (1 paper, 2022). Chronic progressive interstitial lung disorder characterized by the replacement of the lung tissue by connective tissue, leading to progressive dyspnea, respiratory failure, or right heart failure. "Considering the condition that the p-value of survival analysis was less than 0.01 and the p-value of expression difference was less than 0.01, we found that ITK, ZAP70, CD247, and LCK were lower expressed in patients with specific pulmonary fibrosis than in healthy controls." (PMID 35774508, 2022).
sarcoidosis (1 paper, 2023). Sarcoidosis is a multisystemic disorder of unknown cause characterized by the formation of immune granulomas in involved organs. "Given its crucial role in cell signalling, the ZAP70 association with sarcoidosis seems in line with its key role in immunity." (PMID 36653562, 2023). "A >30-fold-enriched missense variant, pThr155Met (rs145955907), in ZAP70 was associated with sarcoidosis (OR = 2.05, P = 1.03 × 10−8)." (PMID 36653562, 2023).
sarcopenia (1 paper, 2020). Progressive decline in muscle mass due to aging which results in decreased functional capacity of muscles. "We observed that the expression of IL1B, BAK1 and SOD1 were significantly increased, while the expression of CDH1, GNG11 and ZAP70 were dramatically decreased in sarcopenia samples compared to those in the controls." (PMID 32226296, 2020).
schizophrenia (1 paper, 2013). A major psychotic disorder characterized by abnormalities in the perception or expression of reality. "The schizophrenia-related SNP study supports the significant result of the involving pathway of translocation of ZAP-70 to immunological synapse by Reactome." (PMID 24564241, 2013).
squamous intraepithelial lesions (1 paper, 2024). "In another study, ZAP70 hypermethylation was reported in all cases of OC and high-grade squamous intraepithelial lesions, whereas no methylation was found in oral lichen planus lesions and healthy individuals, demonstrating a promising role of ZAP70 methylation for early OC detection." (PMID 39138540, 2024).
T-cell immunodeficiency (1 paper, 2025). A broad classification of disorders that affect the cell-mediated aspect of the immune response. "ZAP70 mutations cause T-cell immunodeficiency by disrupting TCR signaling." (PMID 40901120, 2025).
T-cell prolymphocytic leukemia (1 paper, 2012). A slow-growing type of leukemia (blood cancer) in which too many lymphocytes are found in the bone marrow and/or blood. "The highest level of expression obtained was lower than that observed in T-cell prolymphocytic leukemia (T-PLL), but correlated with expression of ZAP-70 and presence of wild-type IGHV genes." (PMID 23064660, 2012).
ulcerative colitis (1 paper, 2025). An inflammatory bowel disease involving the mucosal surface of the large intestine and rectum. "In conclusion, this study provides the first evidence that ceAF can mitigate ulcerative colitis (UC) and TNF-α-induced inflammatory responses by inhibiting the LCK/ZAP70/LAT signaling pathway, thereby reducing TCR signaling hyperactivation." (PMID 39857385, 2025).
uveitis (1 paper, 2018). An inflammatory process affecting a part of or the entire uvea. "According to a recent publication, ZAP70 is a potential biomarker instructing the onset of uveitis in mouse models." (PMID 30349554, 2018). "ZAP70 (ENSP00000264972) is also a functional inferred uveitis-related gene." (PMID 30349554, 2018).
tumor (77 papers, 2006 to 2025). "Although the expression of ZAP-70 in tumor cells has been linked to a dismal outcome, there have only been few attempts to inhibit ZAP-70 as a treatment, partly because the biological functions of ZAP-70 in B cell malignancies remain elusive." (PMID 33194762, 2020). "Our findings identify ZAP-70-associated Rasal1 as a new negative regulator of T-cell activation and tumor immunity." (PMID 31641113, 2019). "The aberrant high ZAP-70 expression found in some mature B cell malignancies may be caused by epigenetic modulation and clonal evolution during tumor transformation." (PMID 33194762, 2020). "The simultaneous targeting of ZAP-70 in tumor cells, T and NK cells, may be beneficial in some instances, but also bears the risk to promote tumor growth through impairing immune surveillance." (PMID 33194762, 2020). "Notably, in a DLBCL case, ZAP-70 deficiency caused complete ablation of the CD8 population in the tumor environment, suggesting a profound effect of ZAP-70 in tumor immune-responses." (PMID 33194762, 2020). "Also, the interaction between PD-1 or PD-2 on the surface of T cells and its ligand PD-L1 on the surface of tumor cells or antigen-presenting calls (APCs) suppresses ζ-chain-associated protein kinase (ZAP70) by SH2 containing protein tyrosine phosphatase-2 (SHP2)." (PMID 36816749, 2023). "MiR-195, known for its tumor-suppressive properties, is significantly downregulated in ZAP-70+ CLL, which correlates with enhanced mitochondrial fitness and cell proliferation via targets such as mitofusin-2 and PRR11." (PMID 40981381, 2025). "ZAP70 is known to influence the tumor microenvironment by mediating interactions between malignant B cells and the surrounding immune cells." (PMID 40901120, 2025). "CD3g and ZAP70 levels were significantly higher in PAK4KO tumour at one week but dropped to similar levels as WT tumour by four weeks." (PMID 38797819, 2024). "And in some reports, silencing ZAP70 has been demonstrated to significantly suppress the anti-tumor capability of CD8 + T cells." (PMID 38400862, 2024). "Multiple immune-associated genes such as CD79A, CD3E, CD3D, ZAP70, CXCR6, and GZMA were upregulated in hot tumor regions." (PMID 38803565, 2024). "Immunohistochemistry results also confirmed that AQP9 and ZAP70 expression was significantly lower in tumor tissues relative to normal tissues." (PMID 35477402, 2022). "Targeting ZAP70 has been debatable as it is challenging to solely target the ZAP70 positive CLL cells to prevent the inactivation of anti-tumor T and NK cell responses." (PMID 35301276, 2022). "We observed the interaction with TSHR-positive tumor cells induced rapid increase of ZAP70 and ERK activities within minutes, indicating antigen-dependent activation of the CAR-Jurkat T cells." (PMID 35252208, 2022). "The differentially expressed analysis revealed that ZAP70 is significantly up-regulated in the tumor group compared with the normal group." (PMID 36636556, 2022). "The significantly lower ZAP-70 expression in BM compared further confirms how powerful is the immune conditioning exerted by the prolonged exposure to tumor cells in the TME." (PMID 36605214, 2022). "Increasing evidence suggests that ZAP-70 down-regulation in T cells and NK cells can contribute to impairment of anti -tumor immune responses and bias the efficacy of immunotherapy." (PMID 36605214, 2022). "The improved biosensor also allowed dynamic imaging of ZAP70 activity during CAR-T/tumor cell engagement." (PMID 34413312, 2021). "Elevated expression level of FYN (p value = 0.000), LCP2 (p value = 0.002), PTPRC (p value = 0.011), WAS (p value = 0.005), ZAP70 (p values = 0.000) and NCF4 (p values = 0.047) were associated with tumor size." (PMID 34834481, 2021). "Of particular interest, in vivo, we observed an additional role for immune signaling pathways (IFNγ, PD-1, and ZAP70) and myeloid leukocyte activation-migration into the tumor microenvironment (TME) to promote immunogenic cell death." (PMID 33499163, 2021).